FGF23 (fibroblast growth factor 23)
Diseases named in the same sentence as FGF23 in open-access papers (continued):
Sharing a sentence is not in itself a finding about the gene and the disease.
alcoholic liver diseases (2 papers, 2024 to 2025). A disorder caused by damage to the liver parenchyma due to alcohol consumption. "Here, we investigated the role of hepatic FGF23 in alcoholic liver disease (ALD) and delineated the underlying molecular mechanism." (PMID 38479224, 2024). "Serum C-terminal FGF23 levels were reported to be significantly greater in chronic alcoholic patients, especially those with alcoholic liver disease, than in normal controls." (PMID 39963340, 2025). "In our previous studies, we reported that ERRγ expression is upregulated in alcoholic liver disease, and ERRγ is a transcriptional regulator of hepatic FGF23 production in mice with FA-AKI and CCl4-ALI." (PMID 38479224, 2024). "To examine the mechanism of FGF23-mediated alcoholic liver damage, we treated WT and FGF23-LKO mice with alcohol and assessed Smac and cytochrome C-mediated apoptotic pathways." (PMID 38479224, 2024). "Taken together, 1 possible hypothesis explaining these effects is that hepatic inflammation due to alcoholic liver disease may induce ectopic secretion of FGF23 in the liver." (PMID 39963340, 2025). "Alcohol induced upregulation of hepatic FGF23 and plasma FGF23 levels is lost in ERRγ-LKO mice, and an inverse agonist mediated inhibition of ERRγ transactivation significantly improved alcoholic liver damage." (PMID 38479224, 2024). "Therefore, we suggest that CB1R-ERRγ-FGF23 signal transduction axis plays a pathological role in chronic alcoholic liver injury through regulating CYP2E1 gene expression, and FGF23 may represent a potential therapeutic target to treat alcoholic liver disease." (PMID 38479224, 2024).
amyloidosis (2 papers, 2020 to 2025). A disorder characterized by the localized or diffuse accumulation of amyloid protein in various anatomic sites. "Furthermore, FGF-23 has been shown to predict outcomes in amyloidosis and acute heart failure." (PMID 41226753, 2025). "Despite the lack of outcome data, our results clearly support that screening for CVD with FMD, FGF23, and hsCRP in patients with FMF and specifically in amyloidosis appears reasonable." (PMID 33110219, 2020). "For patients with GN, FGF23 (HR 1.051 (95% CI 1.019–1.084)) and FMD (HR 0.522 (95% CI 0.300–0.908)) and for patients with amyloidosis, FGF23 (HR 1.035 (95% CI 1.012–1.058)), FMD (HR 0.216 (95% CI 0.109–0.430)) and hsCRP (HR 0.961 (95% CI 0.915–1.009)) independently contributed to the risk of CVDEs." (PMID 33110219, 2020).
and soft tissue neoplasm (2 papers, 2012 to 2016). "PMTMCT is a rare bone and soft tissue neoplasm that is frequently associated with TIO due to secretion of FGF-23." (PMID 23346426, 2012). "Seven PMTs (5 with TIO and 2 without TIO) and 46 other types of bone and soft tissue tumors were retrieved, and immunohistochemistry was performed using a commercially available anti-FGF23 antibody." (PMID 26956379, 2016).
aneurysm (2 papers, 2013 to 2024). Bulging or ballooning in an area of an artery secondary to arterial wall weakening. "In particular, patients with the FGF23 polymorphism had higher serum FGF23 levels (p < 0.01) and developed more frequently coronary artery dilatations or aneurysms (p = 0.05)." (PMID 24168888, 2013). "The presented clinical case is the first and only one in the world to demonstrate the role of this type of FGF23 gene mutation in the development of a hyperphosphatemic variant of tumoral calcinosis characterized by aggressive formation of multiple vascular aneurysms." (PMID 38792634, 2024). "In addition, the FGF23 polymorphism was significantly associated with CaA: indeed, patients presenting with coronary dilatations or aneurysms were significantly more represented in the subgroup with FGF23 polymorphism, compared to wild type FGF23 children (29.2% vs 11.7%, p = 0.05)." (PMID 24168888, 2013).
anorexia nervosa (2 papers, 2008 to 2011). A disorder most often seen in adolescent females characterized by a refusal to maintain a minimally normal body weight, an intense fear of gaining weight, a disturbance in body image, and, in postmenarcheal females, the development of amenorrhea. "In our previous study, binge-eating/purging type anorexia nervosa (AN-BP) patients had elevated plasma intact FGF23 (iFGF23) levels, while restricting type (AN-R) patients had plasma iFGF23 levels similar to healthy controls." (PMID 21682868, 2011). "Our previous study showed that binge-eating/purging type anorexia nervosa (AN-BP) patients had elevated plasma intact FGF23 (iFGF23) levels, while restricting type (AN-R) patients had plasma iFGF23 levels similar to healthy controls." (PMID 21682868, 2011).
bacterial pneumonia (2 papers, 2023). Acute infection of the lung parenchyma caused by bacteria (e.g., Streptococcus pneumoniae, Haemophilus influenzae, Chlamydia pneumoniae, Mycoplasma pneumoniae, and Legionella pneumophila). "Moreover, the administration of FGF23 exacerbated disease and decreased survival, in experimental models of bacterial pneumonia in mice." (PMID 37637614, 2023). "In addition, in experimental models of bacterial pneumonia in CKD mice, the administration of FGF23 exacerbated disease activity and decreased murine survival." (PMID 36828412, 2023).
Calcium nephrolithiasis (2 papers, 2021 to 2024). The presence of calcium-containing calculi (stones) in the kidneys. "There is also a contributing role of FGF-23 and Klotho gene polymorphism in the pathogenesis of calcium nephrolithiasis." (PMID 34249532, 2021). "Little is known about FGF23 levels in patients with calcium nephrolithiasis." (PMID 38186870, 2024).
cerebral atherosclerosis (2 papers, 2019 to 2025). Atherosclerosis of the cerebral vasculature. "Cerebral atherosclerosis, presence of HWMHs and ALIs, total SVD score and fibroblast growth factor-23 were significantly different according to quartiles of the plasma Klotho concentration." (PMID 31398214, 2019).
chronic kidney failure (2 papers, 2015 to 2021). "Elevated fibroblast growth factor 23 (FGF23) levels are associated with adverse outcome in populations with cardiovascular disease and chronic kidney failure." (PMID 34330955, 2021).
colorectal adenoma (2 papers, 2011 to 2020). An adenoma that arises from the colon or rectum. "The purpose of this study was to prospectively evaluate the association between circulating concentrations of FGF-23 and the risk of metachronous (recurrent) colorectal adenomas." (PMID 21383962, 2011). "A statistically significant inverse association between the phosphaturic hormone FGF-23 and odds for metachronous colorectal adenoma was observed." (PMID 21383962, 2011). "FGF-23 levels were assessed in 100 male and female participants from the Ursodeoxycholic Acid Trial, 50 of whom had a metachronous colorectal adenoma and 50 who did not." (PMID 21383962, 2011).
delirium (2 papers, 2023 to 2026). A disorder characterized by confusion; inattentiveness; disorientation; illusions; hallucinations; agitation; and in some instances autonomic nervous system overactivity. "Regarding the Katz index, history of cerebritis (seizure or organic brain syndrome) (n = 12) and the lowest recorded hematocrit to date (values < 30%) (n = 47) were, respectively, associated with higher and lower serum levels of FGF23." (PMID 37627287, 2023). "We corroborated these findings in an independent, age- and sex-matched cohort of 16 patients with similar delirium rates (38%), wherein a significant trend toward higher FGF-23 levels was observed amongst delirious patients." (PMID 42058633, 2026). "Postoperative serum fibroblast growth factor 23 (FGF-23) levels were 3.82-fold higher in patients with delirium and significantly correlated with serum neurofilament light levels." (PMID 42058633, 2026). "A technical validation of the differentially expressed FGF-23 protein via enzyme-linked immunosorbent assays further reinforced the generalizability of our results, suggesting that circulating FGF-23 may serve as a serum biomarker of delirium post-cardiac surgery." (PMID 42058633, 2026).
depression (2 papers, 2024). "For gene expression data, the FGF family is implicated in depression and potentially other psychiatric disorders, with FGF23 levels upregulated in depressive patients following lithium treatment." (PMID 39126426, 2024). "In this study, we found an increase in plasma levels of leptin and OPG, and a decrease in levels of OC, OPN, SOST, PTH and FGF23 after six ketamine infusions in adults with depression, indicating that ketamine may mediate a beneficial effect on BMD." (PMID 38287453, 2024). "First, six infusions of ketamine associated with increased the levels of leptin and OPG, and decreased the levels of OC, OPN, SOST, PTH and FGF23 in patients with depression, which occurred immediately the day after the last infusion (Day 13) and lasted for 2-week post-infusion (Day 26)." (PMID 38287453, 2024).
dermatomyositis (2 papers, 2021). Dermatomyositis (DM) is a type of idiopathic inflammatory myopathy characterized by evocative skin lesions and symmetrical proximal muscle weakness. "We for the first-time evaluated serum FGF-23 in dermatomyositis and related the serum levels to parameters of clinical chemistry and disease activity." (PMID 33546660, 2021). "Importantly, the same study also found higher FGF23 levels in patients with dermatomyositis." (PMID 33895875, 2021). "Some human diseases with enhanced myostatin plasma levels including dermatomyositis and CKD are characterized by enhanced FGF23 production." (PMID 33895875, 2021).
diabetic cardiomyopathy (2 papers, 2020 to 2022). Diabetic cardiomyopathy is a disorder of the heart muscle in people with diabetes. "In rodents and in-vitro studies, FGF-23 has been demonstrated to directly influence cardiomyocytes and induce LV hypertrophy, one of the key characteristic of diabetic cardiomyopathy." (PMID 32998751, 2020).
diabetic foot (2 papers, 2021). A diabetic foot is a foot that exhibits any pathology that results directly from diabetes mellitus or any long-term (or "chronic") complication of diabetes mellitus. "Studies have reported decreased serum Klotho concentrations and increased FGF-23 in patients with diabetic foot, and importantly, these parameters are independently associated with diabetic foot ulcers." (PMID 34721299, 2021). "FGF1, FGF2, FGF4, FGF7, FGF16, FGF21, and FGF23 have been found to have good therapeutic outcomes for diabetic foot ulcers." (PMID 34831463, 2021).
endotoxemia (2 papers, 2021 to 2022). "The results demonstrate that the liver is a source of FGF23 during endotoxemia whereas others have concluded that principally spleen, and to a lesser extent other tissues including bone and thymus, are the organs that produce FGF23 in response to circulating LPS." (PMID 35231062, 2022). "In agreement with the transient nature of LPS-induced endotoxemia, an FGF23 up-regulation of such magnitude and duration has never been reported in LPS-induced endotoxemia." (PMID 33989306, 2021).
fetal growth restriction (2 papers, 2024 to 2025). A fetus that does not grow beyond the 10th percentile of conventionally accepted weight for gestational age. "However, serum fibroblast growth factor-23 levels were found to be lower in pregnancies complicated with gestational hypertensive disease with the presence of fetal growth restriction." (PMID 39045952, 2024).
Gitelman syndrome (2 papers, 2014 to 2022). Gitelman syndrome (GS), also referred to as familial hypokalemia-hypomagnesemia, is characterized by hypokalemic metabolic alkalosis in combination with significant hypomagnesemia and low urinary calcium excretion. "Interestingly, a recent study demonstrated that in the NCC knockout mouse model for Gitelman syndrome, FGF23 levels were increased." (PMID 35137195, 2022). "Therefore, Fgf23−/−/VDRΔ/Δ and Kl−/−/VDRΔ/Δ compound mutants develop a more complex phenotype than Gitelman's syndrome." (PMID 24797667, 2014). "Although Fgf23−/−/VDRΔ/Δ and Kl−/−/VDRΔ/Δ mutants show reduced NCC expression and increased urinary Na+ excretion, they do not develop a typical Gitelman's syndrome." (PMID 24797667, 2014).
glomerulonephritis (2 papers, 2014 to 2015). A renal disorder characterized by damage in the glomeruli. "A recent paper with histologic data from patients with glomerulonephritis showed parallel reduction of renal Klotho and of s-Klotho together with increments in FGF23, which is in agreement with our data." (PMID 25873958, 2015).
glomerulosclerosis (2 papers, 2013 to 2021). A hardening of the kidney glomerulus caused by scarring of the blood vessels. "Spearman's rho rank correlation analysis showed a significant (p<0.0001) positive correlation between the level of renal FGF23 expression and proteinuria (rho = 0.689), glomerulosclerosis (rho = 0.823), tubular damage (rho = 0.787) and interstitial ED1-positive monocytes/macrophages (rho = 0.730)." (PMID 23967103, 2013).
growth disorders (2 papers, 2023 to 2025). "GC can up-regulate the expression of FGF23 in bone and plasma, activating FGFR3 receptors and contributing to GC-induced growth disorders via the FGF23/Klotho/FGFR3 pathway." (PMID 37082116, 2023).
hemangiopericytoma (2 papers, 2020 to 2022). An antiquated term that refers to benign or malignant mesenchymal neoplasms characterized by the presence of neoplastic spindle-shaped to round cells arranged around thin-walled branching vascular spaces. "As regards our patient, postoperative FGF-23 serum concentrations were high above the reference range which (in correlation with imaging tests) suggested an incomplete hemangiopericytoma resection." (PMID 35090436, 2022).
Hyponatremia (2 papers, 2013 to 2023). An abnormally decreased sodium concentration in the blood. "Previously it was shown that in multivariate linear regression analysis, hyponatremia is independently associated with FGF23 level in patients with chronic systolic heart failure." (PMID 37992803, 2023). "Hyponatremia (lower serum [Na+]) has recently been shown to be independently associated with FGF23 levels in patients with chronic systolic heart failure." (PMID 37992803, 2023). "A recent study has shown that hyponatremia is independently associated with FGF23 levels in patients with chronic systolic heart failure." (PMID 37992803, 2023). "We found a positive association between elevated FGF23 levels and hyponatremia in a pilot study conducted in humans." (PMID 37992803, 2023). "However, it remains unclear whether the increased FGF23 levels in hyponatremic patients are primarily influenced by low [Na+] and/or by the underlying cause of hyponatremia." (PMID 37992803, 2023). "Second, the human study is constrained by the limited number of patients available for investigating the impact of hyponatremia on FGF23 levels." (PMID 37992803, 2023). "In line with these in vitro observations, we found that hyponatremia patients have higher FGF23 levels." (PMID 37992803, 2023). "We explored the possibility that hyponatremia might have a direct effect on FGF23 formation." (PMID 37992803, 2023). "Furthermore, arginine vasopressin, which is often responsible for hyponatremia, did not affect FGF23 production." (PMID 37992803, 2023). "While elevated inflammatory cytokines in hyponatremia patients could potentially increase FGF23, we did not detect significantly higher cytokine levels in the patient samples." (PMID 37992803, 2023).
IgA nephropathy (2 papers, 2014 to 2020). "In previous studies, serum levels of FGF23 were elevated in pediatric patients with nephrotic-range proteinuria and in patients with IgA nephropathy and proteinuria." (PMID 32569271, 2020).
infarction (2 papers, 2014 to 2021). A localised pathological necrosis of tissue resulting from obstruction of the blood supply usually by a thrombus, an embolus, or vascular torsion. "The present study aimed to further assess the prognostic association of FGF-23 in a larger, better characterized population with infarction-related CS included in a prospective, randomized clinical trial and to investigate its relationship to renal function." (PMID 25528363, 2014).
internal carotid artery stenosis (2 papers, 2015 to 2025). Carotid stenosis is a narrowing or constriction of the inner surface (lumen) of the carotid artery, usually caused by atherosclerosis. "FGF-23 was consistently and independently associated with unstable plaques, in patients with internal carotid artery stenosis (ICAS), and SMI-assessed intraplaque neovessel count." (PMID 40137447, 2025). "We have found, for the first time, that FGF23 could be associated with unstable plaque in type 2 diabetic patients with internal carotid artery stenosis." (PMID 26459301, 2015). "The object of this study was to investigate the potential role of FGF23 on plaque stability in type 2 diabetic patients with internal carotid artery stenosis." (PMID 26459301, 2015).
kidney transplant (2 papers, 2022 to 2025). A surgical procedure in which one or both kidneys from a donor are implanted into a recipient. "FGF-23 levels are associated with all-cause mortality and graft loss in stable kidney transplant recipients." (PMID 35602513, 2022). "Among long-term kidney transplant recipients, higher FGF-23 is associated with markers of left ventricular wall strain, cardiovascular mortality, and all-cause mortality." (PMID 35602513, 2022). "Among long-term kidney transplant recipients there are persistently high levels of FGF-23 and PTH." (PMID 35602513, 2022). "This study aimed to evaluate the levels of FGF23, Klotho, IL-6, IL-10, and Mstn in relation to subjects without comorbidities in stable kidney transplant recipients receiving triple immunosuppressive therapy." (PMID 41303166, 2025).
malaria (2 papers, 2018). Malaria is a serious and sometimes fatal disease caused by a parasite that commonly infects a certain type of mosquito which feeds on humans. "Plasma levels of the iron status markers hepcidin and fibroblast growth factor 23 were measured in animals surviving and succumbing to malaria, and accompanying tissue pathology in the liver and the spleen was assessed." (PMID 29338760, 2018). "Also, admission levels of ferritin and FGF23 were higher in patients with severe malaria [643 vs 365 μg/L (P = 0.002) and 647 vs 333 RU/mL (P = 0.02), respectively], likely due to inflammation." (PMID 30537973, 2018). "The combination of high FGF23 and low hepcidin levels could possibly serve as a marker of severity of malaria and a predictor for outcome." (PMID 29338760, 2018).
myocardial disease (2 papers, 2014 to 2018). "This close association between FGF-23 and myocardial disease was further confirmed in two recent cohort studies that selectively recruited patients with stable chronic systolic heart failure, among whom FGF-23 independently predicted cardiovascular events and total mortality." (PMID 25528363, 2014). "Moreover, epidemiologic studies suggest that high FGF-23 may follow, rather than induce, myocardial disease in certain conditions." (PMID 30013515, 2018).
nephrotic syndrome (2 papers, 2018 to 2019). A collection of symptoms that include severe edema, proteinuria, and hypoalbuminemia; it is indicative of renal dysfunction. "In the group of children with nephrotic syndrome, concentrations of FGF-23 were significantly higher in the relapse than in the remission, which is also consistent with our results." (PMID 31354894, 2019). "Interestingly, in the group of patients with the first occurrence of nephrotic syndrome, the concentrations of FGF-23 were higher during remission than those during the active phase of the disease." (PMID 31354894, 2019).